EML4 (EMAP like 4)
Diseases named in the same sentence as EML4 in open-access papers (continued):
Sharing a sentence is not in itself a finding about the gene and the disease.
tumor (continued). "The tumor from patient CTC15035EML4–ALK and the CTC15035EML4–ALK xenografts generated from it contained the EML4–ALK gene fusion, and the tumor from patient CTC15063EGFR L858R, T790M and the CTC15063EGFR L858R, T790M xenografts generated from it contained the EGFR mutations, L858R and T790M." (PMID 29764505, 2018). "The goal of our study is to raise awareness of the possible link between EML4-ALK fusion genes and aggravated clinical manifestation and to put forward the opinion that crizotinib is effective, but vigilance is needed in the treatment of this kind of tumor." (PMID 28535796, 2017). "While deletion of WD40 repeats did not impair tumor formation, deletion of the EML4 HELP domain resulted in reduced tumor outgrowth." (PMID 29189709, 2017). "In theory, ALK FISH is capable of detecting any rearrangement involving ALK, regardless of the fusion partners or the EML4-ALK variants, on FFPE tissue which represents the most common method for processing and storing tumor specimens." (PMID 23741400, 2013). "The right tumor and the left one had lepidic growth pattern in common, although the former was EML4-ALK positive, while the latter negative." (PMID 23617234, 2013). "Although PF-02341066 is an effective therapy able to suppress tumor growth in tumors that exhibit positivity for either EML4-ALK or c-Met, it did not affect the intrinsic radiation response of tumor cell lines." (PMID 23254764, 2013). "However, in 16 (64%) of the 25 samples, we found 3 to 4 extra copies of adjacently placed EML4 and ALK signals in 2-50% of the tumor cells." (PMID 24156086, 2013). "Moreover, F-circEA-2a exists in tumor, but not in the plasma of NSCLC patients with EML4-ALK fusion gene, further supporting the significant diagnostic value of F-circEA-4a for EML4-ALK-positive NSCLC." (PMID 30236141, 2018). "Interestingly, patient number 36 presented with an EML4-ALK fusion based on PCR data, but FISH indicated that this patient was ALK rearrangement-negative since there were very few ALK rearrangement-positive cells (approximately 3%) in the tumor." (PMID 28032602, 2017). "The BEAS2B cells are not tumorigenic in nude mice, and in vivo injection of BEAS2B-Mer cells did not form tumor nodules while BEAS2B cells stably expressing EML4-ALK, a well-known transforming oncoprotein, did form subcutaneous xenografts, indicating a lack of transforming activity for Mer." (PMID 25826078, 2015). "Neither age nor tumor stage was correlated significantly with EML4-ALK translocation." (PMID 25789627, 2015). "This is particularly relevant when the tumor is not easily accessible for biologic sample collection and thus oncologists need to spare tissue for fundamental analyses, such as EGFR mutations and EML4-ALK translocation." (PMID 25300933, 2014). "If the tumor is negative, it will be tested for EGFR mutations and EML4-ALK translocation." (PMID 23341890, 2013). "In addition, EML4–ALK was identified by using fluorescent in situ hybridization (FISH) for ALK rearrangements and was confirmed by immunohistochemistry for ALK expression in tumor." (PMID 23714228, 2013). "In addition, research indicates that the EML4-ALK fusion protein may activate the PI3K/AKT signaling pathway to promote the proliferation, survival, and migration of lung cancer cells, thus driving tumor progression." (PMID 40568576, 2025). "While EML4-ALK mRNA can be detected only in the tumor tissues biopsies from non-small-cell lung cancer (NSCLC) patients, detection of F-circEA in plasma of those patients may serve as a potential indicator of EML4-ALK-positive NSCLC and may guide specific EML4-ALK-targeted therapy." (PMID 34572871, 2021). "Further analysis of the expression of F-circEA in the tumor tissues and blood of EML4-ALK-positive patients showed that F-circEA could exist in the plasma and tumor tissues, while the mRNA of the fusion gene EML4-ALK only existed in the tumor tissue and could not be detected in the plasma." (PMID 30400981, 2018).
tumor (continued). "A KIF5B-RET and EML4-ALK fusion were readily detected in the positive control patient-derived xenograft and cell line, but no fusions were detected in 5 of 5 tumor samples." (PMID 39052387, 2024). "For example, the murine EML4-ALK cell lines and the orthotopic model does not recapitulate the time course of tumor development in patients, and likely does not result in the level of heterogeneity observed in human tumors." (PMID 36739466, 2023). "The F-circEA-2a exists in the tumor, but not in the plasma of NSCLC patients with EML4-ALK fusion gene, further indicating that F-circEA has a significant diagnostic value for the diagnosis of EML4-ALK-positive NSCLC." (PMID 32071550, 2020). "EML4-ALK rearrangements were detected in the platelets of 22 patients with EML4-ALK-rearranged tumors and in none of those without EML4-ALK rearrangements in tumor, indicating 65% sensitivity and 100% specificity of the RT-PCR test in platelet RNA." (PMID 26544515, 2016). "Even though PF-02341066 is an effective therapy able to suppress tumor growth in NSCLC tumors that are either EML4-ALK- or c-Met-positive, it did not affect tumor cell radiation resistance in any appreciable manner." (PMID 23254764, 2013). "Since, to our knowledge, no prior studies have investigated tumor stroma-dependent global gene expression changes in TKI-treated EML4-ALK-positive NSCLC, the aim of our study was to explore tumor stroma-related processes leading to nongenetic resistance in this tumor type." (PMID 40524253, 2025). "However, we failed to observe any GFP+ tumour in Krt5 mice (0 out of 130 analysed tumours), suggesting that neither Basal cells from upper airways nor AT1 cells contributed to Eml4-Alk LUAD initiation." (PMID 35931677, 2022). "Indeed, circRNA (F-circEA) produced from the EML4-ALK fusion gene which is independent of the EML4-ALK linear transcript and the fusion protein, can promote migration and invasion, thus contributing to tumor metastasis." (PMID 31185953, 2019). "While we did not break down the analysis by tumor type, the majority (86%) of the analyzed data related to preclinical studies using transformed cell lines, expressing either NPM1-ALK-based constructs or EML4-ALK-based constructs, thus effectively normalizing the analysis." (PMID 30675517, 2019).
cancer (148 papers, 2010 to 2026). A tumor composed of atypical neoplastic, often pleomorphic cells that invade other tissues. "Using these sensors in human cancer cell lines, we identified Ras-interacting proteins in oncogenic EML4-Alk granules and found that Src-Associated in Mitosis 68-kDa (SAM68) protein specifically enhances Ras activity in the granules." (PMID 38273065, 2024). "As these are cancer-derived cell lines, the H3122 (V1) and H2228 (V3) cells harbor additional genetic alterations to the EML4–ALK variants." (PMID 38458397, 2024). "We have also provided a new role for fusion circRNAs in cancers and that F-circEA1 has potential drug resistance to crizotinib, resulting in a novel treatment for EML4-ALK variant 1 positive NSCLC." (PMID 34633654, 2022). "We here find that EML4–ALK variant 1 (exon 1–13 of EML4 fused to exon 20–29 of ALK) forms condensates via phase separation in the cytoplasm of various human cancer cell lines." (PMID 33976114, 2021). "In order to define the structural rules governing higher-order protein assembly, we examined a set of naturally occurring EML4-ALK variants that have been described in cancer patients." (PMID 33848463, 2021). "Ba/F3 cell lines were used, and they either expressed wild type EML4-ALK as a model of ALK-TKI-naïve cancer, or else mutant EML4-ALK with one ALK resistance mutation, mimicking resistance following first- or second-generation ALK inhibitor treatment." (PMID 33572278, 2021). "Echinoderm microtubule-associated protein-like 4 (EML4) is involved in cancers when spliced with the anaplastic lymphoma kinase." (PMID 35008858, 2021). "For specific cancers, proteins encoded by fusion transcripts have been identified as innovative therapeutic targets (e.g., EML4-ALK)." (PMID 32470133, 2020). "We used Snaptron to show the ALKATI variant and related EML4-ALK fusion can be found in non-cancer samples." (PMID 28968689, 2018). "Subsequently, another cancer driver was discovered, a gene rearrangement on chromosome 2, leading to the fusion gene between echinoderm microtubule associated protein like 4 (EML4) and anaplastic lymphoma kinase (ALK)." (PMID 27495736, 2016). "Among 8 EML4-ALK positive carcinomas, there are three cases (37.5%) with variant 2 (V2), two cases (25%) with V5a and one each (12.5%) with variant V1, V3a, or V4a, respectively." (PMID 25407901, 2014). "The EML4-ALK fusion functions in a manner similar to EGFR mutations; that is, EML4-ALK constitutively activates a tyrosine kinase receptor leading to cancer dependence on overactive mitogenic pathways." (PMID 23254764, 2013). "This regulatory axis may be an appealing target for cancer-associated VTE in EML4-ALK fusion NSCLC patients." (PMID 37940761, 2024). "Now that the current data support the role of the axis in the pathogenesis of cancer-associated VTE in EML4-ALK fusion NSCLC cells, the node inhibitors may fulfill a dual purpose in patients with EML4-ALK fusion NSCLC." (PMID 37940761, 2024). "Multiple variants of EML4-ALK form large cytoplasmic protein condensates in cancer cells." (PMID 39488530, 2024). "Transcriptomic analysis of Eml4-Alk-mutant organoids revealed enrichment of genes associated with angiogenesis, including Pdgfb, suggesting that Alk-mutant cancer cells themselves may contribute directly to endothelial cell and pericyte recruitment." (PMID 36192379, 2022). "Hence, studies have tested the efficacy of HSP90 inhibitors in cancer cells with the longer variants of EML4-ALK." (PMID 35884511, 2022). "In this study, we apply Shannon information theory together with optogenetics and live-cell imaging to quantify changes in signal transmission resulting from the expression of the EML4-ALK fusion oncoprotein in the patient-derived STE-1 cancer cell line." (PMID 41214145, 2025). "Once activated, EML4-ALKv3 contributes to disease progression by stabilizing microtubules and enhancing the rate of migration of cancer cells." (PMID 41154634, 2025).
cancer (continued). "Understanding of the molecular event taking place during the development of the ALK‐positive NSCLC, and, in particular, identification of the EML4–ALK protein as a driver of this type of cancer, paved the way to develop targeted therapies." (PMID 41213866, 2025). "Low bitrate in EML4-ALK-positive cells highlights the impaired transmission in cancer cells, which can be at least partially restored by drug treatment." (PMID 41214145, 2025). "YB-0158 (~20% at highest concentration) and Ceritinib (~70%) partially inhibited, whereas co-incubation completely inhibited (~95%), cell growth of EML4-Alk-expressing cancer cells." (PMID 38273065, 2024). "EGFR signaling promotes survival and resistance to ALK inhibitors in EML4-ALK+ cancer cells in vitro, in animal studies, and in patients." (PMID 39488530, 2024). "Co-treatment with YB-0158 and Ceritinib decreased colony formation more than single-drug treatment, and this effect was specific to EML4-Alk-expressing cancer cells." (PMID 38273065, 2024). "Dual inhibition of ALK and ERBB receptors or AKT disrupts RAS/MAPK and AKT/PI3K signalling pathways, and enhances apoptosis in EML4-ALK + NSCLC cancer cells." (PMID 39695132, 2024). "We next measured the ability of EGFR to recruit adapters in EML4-ALK+ cancer cells through co-immunoprecipitation with endogenous EGFR." (PMID 39488530, 2024). "Drug resistance remains a challenge for targeted therapy of cancers driven by EML4-ALK and related fusion oncogenes." (PMID 39488530, 2024). "We used YB-0158 to probe SAM68’s contribution to signaling in the patient-derived EML4-Alk cancer cell lines H3122 (EML4-Alk v1) and H2228 (EML4-Alk v3)." (PMID 38273065, 2024). "For EML4-ALK+ cancers, reactivation of RTKs after ALK inhibition similarly promotes drug tolerance and acquired resistance, although the mechanisms of reactivation are not well understood." (PMID 39488530, 2024). "Overexpression of GRB2-GFP exerted effects on both basal and stimulated EML4-ALK cancer cells, in a manner dependent on GRB2 expression levels." (PMID 39488530, 2024). "Our results reveal an apparently paradoxical function for EML4-ALK assemblies in cancer cells and their response to targeted therapy." (PMID 39488530, 2024). "The molecular mechanisms we find to underlie these events likely contribute to previously observed synergies in multiple combination therapies and propose treatment co-targets to enhance therapy in EML4-ALK+ cancers." (PMID 39488530, 2024). "EML4-ALK fusions have also been identified in other cancer types such as metastatic colon cancer and breast cancer, suggesting the use of TKIs as part of the treatment plan to disrupt the kinase cascade in triggered oncogenic signaling." (PMID 36734129, 2023). "For further investigations of the molecular mechanisms mediating variation in the depth and duration of response, we developed a panel of transplantable murine EML4-ALK cancer cell lines derived from this model." (PMID 36739466, 2023). "Crizotinib is a first-generation, oral, small-molecule ALK-TKI that was FDA approved in 2011 to treat cancers expressing EML4-ALK gene fusions." (PMID 36734129, 2023). "The translocation and fusion of echinoderm microtubule-associated protein-like 4 (EML4) and anaplastic lymphoma kinase (ALK) have been implicated in various cancers." (PMID 36303815, 2022). "Considerable research has focused on elucidating the mechanisms behind EML4-ALK fusion-driven cancer progression, largely due to the fact that they are the most common ALK rearrangement in NSCLC." (PMID 35884511, 2022). "We used two cancer cell lines that express oncogenic KRas, and two cell lines that have EML4/ALK as the oncogenic driver." (PMID 36686777, 2022). "An incomplete understanding of the mechanisms underpinning EML4-ALK-driven cancer progression and how resistance develops presents a challenge to the search for alternative treatments and emphasizes the need for further research." (PMID 35884511, 2022).
cancer (continued). "This is a vaccine treatment design based on specific CTLs against EML4-ALK positive cancer cells, and further research and analysis are still required in order to realize the application of this type of vaccine in ALK positive NSCLC patients." (PMID 36591504, 2022). "Resistance to cancer therapies like cirzotinib against fusion oncogenic proteins, such as EML4-ALK in non-small cell lung cancer (NSCLC), can be explained by a localizer c-mod mechanism of action." (PMID 36483537, 2022). "In summary, our results indicate that ALK inhibition triggers LC3B-independent macroautophagic flux in EML4-ALK+ cells to support cancer cell survival and clonogenic growth." (PMID 33907223, 2021). "US8969336B2 states diamino heterocyclic carboxamide derivatives as having outstanding inhibitory activity against EML4-ALK fusion proteins for use in cancer therapy." (PMID 34451807, 2021). "To understand the localization and protein properties of EML4–ALK, we transiently expressed GFP–EML4–ALK variant 1 in HeLa cells, a commonly-used human cancer cell line." (PMID 33976114, 2021). "To investigate why CCDC6-RET protein granule formation is kinase-independent, we swapped the fusion partners EML4 and CCDC6 to generate two additional oncogenic RTK fusion oncoproteins that are also present in human cancers, EML4-RET and CCDC6-ALK." (PMID 33848463, 2021). "We orthogonally confirmed recruitment of the key adaptor, GRB2, to endogenous EML4-ALK cytoplasmic protein granules detected by IF in patient-derived cancer cells (H3122), as well as through dual expression of EML4-ALK and GRB2 in Beas2B cells." (PMID 33848463, 2021). "A mouse xenograft model of resistance to lorlatinib was engineered with cancer cells deriving from a sensitive EML4-ALK v1 cell line, namely MGH006." (PMID 33572278, 2021). "Our study here shows that EML4–ALK forms condensates via phase separation in human cancer cell lines and mouse lung tumors." (PMID 33976114, 2021). "We focused our initial study on EML4-ALK variant 1, the most common oncogenic form in human cancers." (PMID 33848463, 2021). "Subsequently, the antiproliferative effects of endogenous cc domain co-expression and mimetic cc peptides were assayed in EML4-ALK cancer cell lines." (PMID 32300555, 2020). "The Eml4-Alk fusion protein generated after rearrangement between Eml4 and Alk promotes cancer development." (PMID 32591530, 2020). "We thank Dr. Katayama and Dr. Uchibori from the Japanese Foundation for Cancer Research (Tokyo, Japan) for providing Ba/F3 cells and the EML4-ALK construct and advice on research." (PMID 32300555, 2020). "Proliferation of cancer cells expressing EML4-ALK fusion typically depends on the downstream signaling of this oncogene, making it an attractive target for chemotherapy treatments." (PMID 32344689, 2020). "In cancer development, however, ALK took the spotlight when it was discovered that the ALK gene is fused to echinoderm microtubule-associated protein like 4 (EML4) on chromosome 2 in NSCLC." (PMID 30404198, 2018). "Nevertheless, since CTCs typically constitute of a few cancer cell per tens of millions of normal nucleated cells in the blood, their use for the detection of EML4-ALK rearrangements must rely on novel CTC detection strategies." (PMID 26544515, 2016). "We assess the effects of these mutations on the activity of six clinical inhibitors in independent systems engineered to depend on either the ALCL fusion kinase NPM-ALK or the lung-cancer fusion kinase EML4-ALK." (PMID 27009859, 2016). "The intracellular localisation of the most common EML4-ALK variant proteins has been studied in model cell lines and in cancer cells derived from patients." (PMID 26755435, 2016). "ALK signalling is activated in cancer cells through three principal mechanisms: gene fusion events, such as NPM-ALK and EML4-ALK; ALK gene amplification; and activating point mutations such as F1174L in neuroblastoma." (PMID 26755435, 2016).